LMTK2 (lemur tyrosine kinase 2)
Description:
Phosphorylates PPP1C, phosphorylase b and CFTR.
Synonyms: hBREK; CPRK; AATYK2; BREK; KIAA1079; KPI2; LMR2; KPI-2; PPP1R100
Tractability: Small molecule: it belongs to a druggable protein family. Antibody: UniProt predicts a signal peptide or a membrane-spanning region; the Human Protein Atlas places it where antibodies can reach. PROTAC: ubiquitination databases record sites on it; its protein half-life has been measured.
Target class: Enzyme; Transferase
Gene: Protein-coding gene on chromosome 7 (98,106,860 to 98,209,638, forward strand). Ensembl gene ENSG00000164715.
Subcellular location: Membrane
Subcellular location (Human Protein Atlas): Centriolar satellite; Nuclear speckles; Cytosol; Plasma membrane
Gene Ontology:
Molecular function: myosin VI binding; protein binding; protein phosphatase inhibitor activity; protein serine/threonine kinase activity; ATP binding; protein kinase activity; protein serine kinase activity
Biological process: early endosome to late endosome transport; endocytic recycling; peptidyl-serine phosphorylation; peptidyl-threonine phosphorylation; protein autophosphorylation; protein phosphorylation; receptor recycling; transferrin transport
Cellular component: early endosome; Golgi apparatus; membrane; perinuclear region of cytoplasm; recycling endosome; cytoplasm; endomembrane system; growth cone; neuronal cell body
Genetic constraint (gnomAD): Loss-of-function variants: 32 observed, 105.36 expected, observed/expected ratio (o/e) 0.3, 90% interval 0.23 to 0.41. The upper end of that interval is the gene's LOEUF score, 0.41, which puts it in group 1 of 6, group 1 being the genes least tolerant of losing a copy. Missense variants: 1,555 observed, 1,790.4 expected, observed/expected ratio (o/e) 0.87, 90% interval 0.83 to 0.91. Synonymous variants: 763 observed, 763.28 expected, observed/expected ratio (o/e) 1, 90% interval 0.94 to 1.06.
Homologues: Orthologues: chimpanzee LMTK2 (99% identical), macaque LMTK2 (93% identical), dog LMTK2 (83% identical), guinea pig LMTK2 (81% identical), mouse Lmtk2 (76% identical), rat Lmtk2 (76% identical), pig LMTK2 (74% identical), rabbit LMTK2 (68% identical), tropical clawed frog lmtk2 (47% identical), zebrafish lmtk2 (41% identical). Paralogues in human: EPHB6 (11% identical), PDGFRB (10% identical), EPHB2 (10% identical), EPHA5 (10% identical), FLT1 (10% identical), FGFR2 (10% identical), FLT4 (10% identical), PDGFRA (10% identical), KDR (10% identical), FGFR1 (9% identical), EPHB3 (9% identical), EPHA1 (9% identical), and 41 more.
Diseases named in the same sentence as LMTK2 in open-access papers:
LMTK2 is named in the same sentence as 44 diseases in open-access papers, as found by Europe PMC text mining. Sharing a sentence is not in itself a finding about the gene and the disease. The quoted sentences say what the papers report.
prostate carcinoma (17 papers, 2010 to 2024). A carcinoma that arises from epithelial cells of the prostate gland. "Among them, LMTK2 has been identified as a susceptibility gene in prostate cancer and several other studies also highlighted that changes in LMTK2 and LMTK3 expressions can also be used as prognostic markers in colorectal, gastric, prostate and breast cancers." (PMID 38191649, 2024). "Other risk alleles have been shown to affect gene expression, such as rs6465657 on LMTK2 expression, a gene implicated in the development of prostate cancer." (PMID 29560112, 2018). "Our data shows that loss of LMTK2 protein is strongly associated with prostate cancer and prostate hyperplasia, disease states marked by dysregulation of AR." (PMID 26008968, 2015). "Our study shows that a decrease in LMTK2 expression is associated with human prostate cancer and that LMTK2 and AR are binding partners in prostate epithelial cells." (PMID 26008968, 2015). "Since, we did not genotype prostate cancer tissues it remains to be determined if SNP rs6465657 associated with prostate cancer results in decrease in LMTK2 protein expression." (PMID 26008968, 2015). "This provides further evidence for a role of LMTK2 in determining susceptibility to prostate cancer." (PMID 20569440, 2010). "Indeed, LMTK2 gene polymorphisms associated with decreased LMTK2 mRNA and protein levels were found in prostate cancer tissues." (PMID 33816229, 2021). "The rs6465657 variant of LMTK2 was evidently related to the development of prostate cancer." (PMID 31722712, 2019). "Among the SNPs that are in high LD with the prostate cancer index SNPs, our results highlight one of the missense SNPs rs11765552, in high LD (r2 = 0.99) with the index risk SNP rs6465657, as being located in the LMTK2 gene." (PMID 25658610, 2015). "Previous studies have suggested that reduced LMTK2 mRNA levels are associated with prostate cancer, however whether this translates to altered protein levels has not been determined." (PMID 26008968, 2015). "Recently, several Genome Wide Association Studies (GWAS) involving prostate cancer patients of Caucasian and East Asian descent identified a genetic variant (SNP rs6465657) of Lemur Tyrosine Kinase 2 (LMTK2), leading to decrease in its mRNA expression, to be associated with prostate cancer." (PMID 26008968, 2015). "The statistical significance of apparent differences in LMTK2 expression between normal, and prostate cancer was investigated by Mann-Whitney-U analysis for pairwise comparison, which revealed a strong association (P ≤ 0.001) between a decrease in LMTK2 protein expression and prostate cancer." (PMID 26008968, 2015). "It was surprising to find LMTK2 to be localized in a nuclear fraction of prostate cancer cells as previous studies have suggested LMTK2 to be an endosomal-membrane associated kinase though none looked specifically for nuclear localization." (PMID 26008968, 2015). "In order to better understand the physiological role of LMTK2 in prostate cancer, we investigated the effect of LMTK2 on the tumor forming capacity and cell viability of LNCaP cells, using a tumorsphere assay and a cell viability assay." (PMID 26008968, 2015). "The role of LMTK2 in cells is just beginning to be unraveled, but appears to play important roles in ion channel trafficking, androgen signaling in prostate cancer and neuro-degeneration." (PMID 26559041, 2015). "In conclusion, our findings are the first evidence that LMTK2 negatively regulates AR activity in prostate cancer cells possibly by directly interacting with AR." (PMID 26008968, 2015). "In terms of potential therapeutic target, small molecules that enhance the activity of LMTK2 can decrease AR-proliferative activity in patients with prostate cancer and more importantly with castrate resistant prostate cancer." (PMID 26008968, 2015).
prostate carcinoma (continued). "Results obtained from human prostate cancer cell and tissue model together shows that AR and LMTK2 are binding partners suggesting a functional significance of LMTK2 in AR-axis." (PMID 26008968, 2015). "Data in this paper shows that decreasing LMTK2 expression in prostate cancer cells deprived of androgen results in significantly higher levels of FKBP51 protein as well as increased mRNA levels of AR-dependent genes (KLK2, S100P, TMPRS22 and PSA)." (PMID 26008968, 2015). "We confirm that not only is LMTK2 mRNA reduced in prostate cancer tissue, but also LMTK2 protein levels are markedly diminished." (PMID 26008968, 2015). "Our report shows that LMTK2 is an essential negative regulator of AR transcriptional activity and knocking down its expression in prostate cancer cells leads to significant increase in the AR activity and also an increase in tumorogenecity and cell viability." (PMID 26008968, 2015). "Given GWAS linking LMTK2 expression levels with prostate cancer, we initially determined if LMTK2 was expressed in prostate epithelia." (PMID 26008968, 2015). "In this report, we compared protein expression of LMTK2 in human prostate cancer tissue specimens with normal, hyperplasia and prostate tissue specimens." (PMID 26008968, 2015). "Our finding that LMTK2 is a negative regulator of AR activity defines a novel cellular pathway for activation of AR-responsive genes in castrate resistant-prostate cancer." (PMID 26008968, 2015). "Initial evidence supporting this possibility comes from our study where we show LMTK2 and AR to be binding partners in prostate cancer cells." (PMID 26008968, 2015). "We found that expression levels of the LMTK2 gene were also inversely correlated with the presence of prostate cancer." (PMID 20569440, 2010). "LMTK2 was proposed as a potential biomarker and therapeutic target for prostate cancer." (PMID 33816229, 2021). "The role of LMTK2 in prostate cancer has been well established." (PMID 33816229, 2021). "The second study examined the expression level of LMTK2 in blood samples of prostate cancer patients, with the aim of making use of LMTK2 level as a potential biomarker for stratification between clinically insignificant and clinically significant PCa patients." (PMID 34064250, 2021). "The role of LMTK2 has been investigated in several malignancies, particularly in prostate cancer." (PMID 32012723, 2020). "Previous studies have focused mainly on the biological function of LMTK2 in prostate cancer." (PMID 31722712, 2019). "Moreover, LMTK2-Knock Down (KD) in prostate cancer cells results in an increase in cell viability and tumorogenecity in the presence and absence of androgen." (PMID 26008968, 2015). "Immunostaining analysis of a human prostate tissue array (US Biomax) containing prostate cancer (n = 48), prostate hyperplasia (n = 8) and normal prostate tissue (n = 14) from a total of 20 individual patients, revealed a marked difference in LMTK2 protein expression levels." (PMID 26008968, 2015). "Hence, a reasonable expectation was that LMTK2 would be localized in the extra-nuclear membrane fraction of prostate cancer cells." (PMID 26008968, 2015). "We undertook evaluation of the role of Lemur Tyrosine Kinase 2 (LMTK2) in modulating AR activity, as several Genome Wide Association Studies (GWAS) have shown a marked association of LMTK2 activity with the development of prostate cancer." (PMID 26008968, 2015). "In addition, LMTK2 knockdown led to an increase in prostate cancer stem cell populations in LNCaP cells, indicative of increased tumorogenicity." (PMID 26008968, 2015). "Hence, it can be deduced that a decrease in LMTK2 expression observed in prostate cancer patient promotes tumor cells proliferation by enhancing AR transcriptional activity." (PMID 26008968, 2015).
prostate carcinoma (continued). "In contrast, knock down of LMTK2 in HEK293 cells expressing AR (analogous to prostate cancer cells) enhanced androgen-dependent activation of reporter gene by three fold in comparison to parental cells and by six fold in comparison to cells overexpressing LMTK2." (PMID 26008968, 2015). "Moreover, pharmacologic manipulation of LMTK2 activity will provide a novel therapeutic target for more effective treatments for patients with castrate-resistant prostate cancer." (PMID 26008968, 2015). "Recent Genome Wide Association Studies (GWAS) of patients with prostate cancer have identified a genetic variant of Lemur Tyrosine Kinase 2 (LMTK2) (also called BREK/KPI-2/CRPK/AATYK2), a membrane associated kinase to be strongly associated with prostate cancer (P < 0.0001)." (PMID 26008968, 2015). "Therefore, it would be interesting to determine if this missense SNP generates a form of LMTK2 with differential binding capacity for myosin VI, ultimately affecting intracellular trafficking and the endosomal secretory pathway in prostate cancers." (PMID 25658610, 2015). "Furthermore, LMTK2 immunostaining and duolink data in this report indicates a nuclear translocation of LMTK2/AR complexes in response to androgen treatment of prostate cancer cells." (PMID 26008968, 2015). "In addition, cell viability data showed the strongest role of decrease in LMTK2 in regards to androgen-independent growth in prostate cancer cells, androgen-dependent growth was also affected, although to a lesser degree." (PMID 26008968, 2015). "Furthermore, targeted activation of LMTK2 in the prostate tissues by small molecules could decrease the AR-proliferative activity, preventing the prostate cancer cell growth." (PMID 30761001, 2019). "Furthermore, the LMTK2 single nucleotide polymorphism (SNP), rs6465657 was inversely associated with the risk of non-fatal prostate cancer and the cancer-specific mortality." (PMID 30761001, 2019). "Interestingly, LMTK2 negatively regulates AR expression in prostate cancer cells and decreased expression of LMTK2 has been observed in prostate cancer, indicating that the regulatory mechanisms between AR and LMTK2 in RCC and prostate cancer may be different." (PMID 26814892, 2016). "Furthermore, loss of LMTK2, associated with prostate cancer can enhance AR transcriptional activity in absence of androgen, suggesting role of LMTK2 in development of CRPC." (PMID 26008968, 2015). "However, due to limited understanding of LMTK2 function, its role in prostate cancer still remains unknown." (PMID 26008968, 2015). "In this regard, five mRNAs (CCND1, LMTK2, FN1, EZH2, and GOLM1) were included in a gene panel for prostate cancer diagnosis and reported as differentially expressed in a Chinese cohort of 281 patients using RT-qPCR from tissue samples." (PMID 39595075, 2024). "Our results indicate that the amount or nature of mRNA transcripts expressed from the LMTK2, HNF1B and MSMB candidate genes is altered in prostate cancer, and provides further evidence for a role for these genes in this disorder." (PMID 20569440, 2010). "The LMTK2 expression had no significant ethnic heterogeneity, as demonstrated in multi-ethnic prostate cancer populations from California with African and Latino background, or from Hawaii from native, Japanese or European descent." (PMID 30761001, 2019). "Confocal imaging and subcellular fractionation studies detected LMTK2 in nuclear and non-nuclear compartments in prostate cancer cells." (PMID 30761001, 2019). "We further confirmed this finding using subcellular fractionation, to enrich a nuclear fraction, which too showed presence of LMTK2 in nuclear and non-nuclear compartment of prostate cancer cells, irrespective of its androgen exposure." (PMID 26008968, 2015). "Surprisingly, our confocal images showed both nuclear as well as non-nuclear staining for LMTK2 in prostate cancer cells." (PMID 26008968, 2015).
prostate carcinoma (continued). "Furthermore, we also show a high-level expression of LMTK2 in normal prostate epithelial cells (PNT1A), androgen-independent metastatic prostate cancer cells (PC3), androgen-dependent prostate cancer cells (LNCaP) and mouse primary prostate epithelial cells." (PMID 26008968, 2015). "We report here that disruption of the amount or nature of transcripts expressed from the LMTK2, MSMB and HNF1B genes, identified in the genome wide scans for prostate cancer, may be important in the aetiology of this disorder." (PMID 20569440, 2010). "In addition, LMTK2 protein abundance was undetectable or low in prostate cancer tissues, compared to very high expression in non-malignant tissue." (PMID 30761001, 2019). "Since, the AR is active in CRPC and is able to transcribe AR-dependent genes either in the presence of low levels of androgens or absence of androgens, we determined if a decrease in LMTK2 is involved in activating AR in androgen deprived prostate cancer cells." (PMID 26008968, 2015). "An important question that arises from our study is the mechanism by which LMTK2 might be regulating AR transcription and cell proliferation in the absence of exogenous androgen in prostate cancer cells." (PMID 26008968, 2015). "Furthermore, a decrease in LMTK2 protein expression, as proposed in prostate cancer, not only results in an increase in androgen mediated AR activity but also increases the androgen-independent activity of AR." (PMID 26008968, 2015).
Alzheimer disease (7 papers, 2018 to 2024). A progressive, neurodegenerative disease characterized by loss of function and death of nerve cells in several areas of the brain leading to loss of cognitive function such as memory and language. "Fourthly, LMTK2 can be involved in the microtubule-associated protein tau hyperphosphorylation in Alzheimer’s disease and other tauopathies." (PMID 39520508, 2024). "Abnormal accumulation of cdk5/p35 in neuronal cell body have been observed in affected brain regions in post-mortem Alzheimer’s disease brains which is consistent with disrupted cdk5/p35 transport caused by loss of LMTK2." (PMID 39520508, 2024). "Loss of LMTK2 may therefore contribute to Alzheimer’s disease by effects on axonal transport of p35 and cdk5." (PMID 31068217, 2019). "Since we show that LMTK2 mediates axonal transport of p35 and cdk5, this loss of LMTK2 may contribute to the cell body cdk5/p35 accumulation that has been described in Alzheimer’s disease." (PMID 31068217, 2019). "The loss of LMTK2 that we describe in Alzheimer’s disease brains may therefore impact on both axonal transport and neuronal signaling functions which are all perturbed in dementia." (PMID 31068217, 2019). "Since siRNA loss of LMTK2 perturbed axonal transport of both p35 and cdk5, we enquired whether LMTK2 levels might be altered in Alzheimer’s disease." (PMID 31068217, 2019). "This virtual contradiction can be explained by the decreased LMTK2 expression in Alzheimer’s disease." (PMID 39520508, 2024). "Of interest therefore were our findings that LMTK2 levels are reduced in Alzheimer’s disease cortex (affected region) and that this reduction occurs in mid (Braak stage III-IV) as well as severe (Braak stage VI) dementia cases." (PMID 31068217, 2019). "In contrast to the Alzheimer’s disease cortex, LMTK2 levels were elevated in Braak stage VI cerebellum." (PMID 31068217, 2019). "In this context it is noteworthy that as we show in the post-mortem human tissues, LMTK2 levels are also reduced in cortex and increased in cerebellum in some transgenic mouse models of Alzheimer’s disease." (PMID 31068217, 2019). "To do so, we monitored LMTK2 levels by immunoblotting in post-mortem Alzheimer’s disease brain tissues." (PMID 31068217, 2019). "Additionally, in the case of at least in LMTK2, reduced LMTK2 expression is an early pathological phenomenon in Alzheimer’s disease and early anomalies are generally believed to contribute the most to the disease pathogenesis." (PMID 39520508, 2024). "Notably, decreased LMTK1 and LMTK2 protein expressions have been detected in the cortex and hippocampus of Alzheimer’s disease patients." (PMID 39520508, 2024). "Finally, we show that LMTK2 levels are reduced in affected regions in post mortem Alzheimer’s disease brains." (PMID 31068217, 2019). "Finally, we show that LMTK2 levels are reduced in affected cortical regions in post-mortem Alzheimer’s disease brains." (PMID 31068217, 2019). "Progressively decreasing LMTK2 levels seen in an Alzheimer’s disease mouse model could potentially lead to aberrant overactivation of GSK3β in aged mice." (PMID 29631601, 2018). "Finally, LMTK1 and LMTK2 protein expressions are decreased in Alzheimer’s disease." (PMID 39520508, 2024). "Finally, we show that LMTK2 levels are reduced in Alzheimer’s disease brains." (PMID 31068217, 2019). "Thus, LMTK2 binds to KLC1 to direct axonal transport of p35 and its loss may contribute to Alzheimer’s disease." (PMID 31068217, 2019). "Moreover, LMTK2 gene expression is decreased in an Alzheimer’s disease mouse model." (PMID 29631601, 2018). "Interestingly, LMTK2 expression changes differently in affected (frontal cortex) and non-affected (cerebellum) brain regions in Alzheimer’s disease post-mortem brains." (PMID 39520508, 2024).